FILIP1L (filamin A interacting protein 1 like)
Diseases named in the same sentence as FILIP1L in open-access papers (continued):
Sharing a sentence is not in itself a finding about the gene and the disease.
cancer (continued). "Both mRNA and protein expression of FILIP1L were down-regulated in these cancer cells compared with their normal epithelial cells." (PMID 24340050, 2013). "At least one study has indicated that endostatin treatment sensitizes cancer cells to killing by doxorubicin, although it is unclear if this model involves increased FILIP1L expression." (PMID 22900064, 2012). "Additionally, vitamin C and buparlisib co-treatment changed the expression of genes, including PCNA and FILIP1L, which are critical to cancer growth and metastasis." (PMID 33664847, 2021). "Further, the modulation of FILIP1L expression may have the potential to be a target for cancer therapy." (PMID 27776341, 2016). "Moreover, FILIP1L expression is decreased in various cancer tissues, suggesting that FILIP1L suppresses cancer development and progression." (PMID 27750216, 2016). "Modulation of FILIP1L expression in these cancer cells led to the changes in cell invasion." (PMID 27776341, 2016). "However, the clinical relevance of FILIP1L down-regulation in cancer progression has yet to be addressed." (PMID 27776341, 2016). "Since FILIP1L expression is inversely correlated with cancer invasiveness/aggressiveness in various other cancer types, these studies will also have an impact on treatment of other cancers." (PMID 27776341, 2016). "A significant inverse correlation was present in all four cancer histologies, suggesting that DNA methylation in the FILIP1L promoter may mediate FILIP1L down-regulation in various cancer histologies." (PMID 24340050, 2013). "To further test if epigenetic regulation results in re-expression of FILIP1L, we treated the four lowestFILIP1L-expressing cancer cell lines from each cancer histology (BT-549, HT-29, H1299 and MIA PaCa-2) with either a DNA demethylating agent or histone deacetylase inhibitor." (PMID 24340050, 2013). "Therefore, it will be of interest to identify the mechanism by which FILIP1L inhibits cancer cell invasion and metastasis in these various cancer histologies." (PMID 24340050, 2013). "Based on these observations, we asked whether FILIP1L expression was also down-regulated in other human cancer histologies and whether it was inversely correlated with the degree of invasive potential." (PMID 24340050, 2013). "Along with the findings from the present study, it suggests that FILIP1L may be utilized as a cancer therapeutic, which can inhibit cancer metastasis as well as angiogenesis." (PMID 24340050, 2013). "Taken together, these data suggest that the degree of FILIP1L expression may be a predictor of cancer cell behavior and, further, that the modulation of FILIP1L expression in various cancers may be a useful target for the development of novel cancer therapies." (PMID 24340050, 2013). "Overall, these findings suggest that FILIP1L may be an important inhibitor of cancer cell invasion and metastasis." (PMID 24340050, 2013). "Thus, modulation of FILIP1L expression has the potential to be a target for cancer therapy." (PMID 24340050, 2013). "In addition, the FILIP1L mRNA expression demonstrated a significant inverse correlation with invasiveness of the cells, suggesting that FILIP1L expression is inversely correlated with the invasive potential of all four cancer cell lines." (PMID 24340050, 2013). "Thus, findings from the present study suggest that FILIP1L could be down-regulated and inversely correlated with the invasive potential of many human cancer histologies." (PMID 24340050, 2013). "Filamin A interacting protein 1-like (FILIP1L) expression, which is decreased in various cancers, may inhibit carcinogenesis." (PMID 27750216, 2016). "We transfected these various cancer cells with either non-targeting or FILIP1L siRNA and measured invasion." (PMID 24340050, 2013).
cancer (continued). "However, TSA treatment also resulted in increased FILIP1L mRNA in cancer cells from other histologies such as colon, lung and pancreas, which suggests that DNA methylation is not the only mechanism by which FILIP1L is down-regulated in these cells." (PMID 24340050, 2013). "Although there still no studies revealed the roles of FILIP1L and TOM1L1 in m6A modification, their functions in cancer have been preliminarily described." (PMID 40303916, 2025). "Thus, we believe it would be important to confirm if FILIP1L is down-regulated in tissues of other cancer histologies such as breast, colon, lung and pancreas, and whether or not FILIP1L promoter methylation is a mechanism by which FILIP1L is down-regulated in these cancer tissues." (PMID 24340050, 2013).
adenocarcinoma (1 paper, 2022). A common cancer characterized by the presence of malignant glandular cells. "Filip1l CKO mice were monitored up to a year; however, we have not observed adenocarcinoma formation." (PMID 36860703, 2022).
FILIP1L also shares sentences with these, for which no sentence is quoted: fibrosis (1 paper); glioma (1); infection (1); invasive carcinoma (1); ovarian tumor (1); serous carcinoma (1); Tetralogy of Fallot (1).